ISM1 (isthmin 1)
Description:
Acts as an angiogenesis inhibitor.
Synonyms: C20orf82; ISM; bA149I18.1; Isthmin; dJ1077I2.1
Tractability: Antibody: UniProt places it where antibodies can reach, with high confidence; UniProt predicts a signal peptide or a membrane-spanning region; its Gene Ontology location is reachable by antibodies, with medium confidence.
Gene: Protein-coding gene on chromosome 20 (13,221,274 to 13,300,651, forward strand). Ensembl gene ENSG00000101230.
Subcellular location: Secreted
Gene Ontology:
Biological process: negative regulation of angiogenesis
Cellular component: extracellular region
Genetic constraint (gnomAD): Loss-of-function variants: 25 observed, 42.76 expected, observed/expected ratio (o/e) 0.58, 90% interval 0.43 to 0.82. The upper end of that interval is the gene's LOEUF score, 0.82, which puts it in group 3 of 6, group 1 being the genes least tolerant of losing a copy. Missense variants: 528 observed, 602.35 expected, observed/expected ratio (o/e) 0.88, 90% interval 0.81 to 0.94. Synonymous variants: 252 observed, 241.46 expected, observed/expected ratio (o/e) 1.04, 90% interval 0.94 to 1.16.
Homologues: Orthologues: macaque ISM1 (98% identical), dog ISM1 (96% identical), pig ISM1 (95% identical), rabbit ISM1 (94% identical), mouse Ism1 (93% identical), chimpanzee ISM1 (92% identical), guinea pig ISM1 (91% identical), rat Ism1 (86% identical), tropical clawed frog ism1 (76% identical), zebrafish ism1 (68% identical), Drosophila melanogaster Tsp (13% identical). Paralogues in human: THBS4 (19% identical), THBS2 (19% identical), THBS1 (18% identical), THBS3 (17% identical), COMP (13% identical).
Diseases named in the same sentence as ISM1 in open-access papers:
ISM1 is named in the same sentence as 63 diseases in open-access papers, as found by Europe PMC text mining. Sharing a sentence is not in itself a finding about the gene and the disease. The quoted sentences say what the papers report.
diabetes (12 papers, 2021 to 2025). "Our analysis indicated that Ism1 and TG are significantly and independently associated with pre-diabetes and T2D." (PMID 39857685, 2025). "Previous studies have reported that ISM1 levels improved glucose tolerance and were associated with a lower risk of diabetes." (PMID 39119006, 2024). "Elevated levels of Ism1 are associated with a reduced risk of diabetes." (PMID 40142334, 2025). "Additionally, our findings indicate that low levels of Ism1 are significantly associated with an increased risk of developing pre-diabetes and T2D." (PMID 39857685, 2025). "The significant association implies that maintaining higher levels of Ism1 may be beneficial in reducing the risk of transitioning from normal glucose regulation to pre-diabetes and subsequently to T2D." (PMID 39857685, 2025). "Moreover, ISM1 expression in adipocytes and circulating ISM1 levels have been associated with obesity and reduced risk of type 2 diabetes mellitus (T2DM)." (PMID 38066623, 2023). "Considering high prevalence of Nonalcoholic Fatty Liver Disease in patients with type 2 diabetes and the regulating role of Ism1 on glucose uptake of peripheral tissues, we further explored the association between Ism1 and diabetes-associated nonalcoholic fatty liver disease." (PMID 35712241, 2022). "Our data has confirmed that Ism1 was an independent protective factor for the development of T2D, so Ism1 and adipokines may be used to build models to predict the risk of diabetes in the population." (PMID 35712241, 2022). "Consequently, further prospective clinical trials were required to demonstrate the predictive value of Ism1 for identifying the risk of diabetes in the population." (PMID 35712241, 2022). "Therefore, we intended to examine the difference in serum levels of Ism1 from newly-onset type 2 diabetes and normoglycemic controls, and analyzed the relationship between Ism1 level and the risk of diabetes by logistic regression." (PMID 35712241, 2022). "Serum Ism1 levels were almost the same in the control group and patients with newly diagnosed diabetes (p = 0.923)." (PMID 40142334, 2025). "This highlights the importance of further research into Ism1’s mechanisms and its potential as a target for therapeutic strategies aimed at preventing diabetes onset." (PMID 39857685, 2025). "Many studies have shown that the abnormal expression or function of ISM-1 is closely related to the occurrence and development of diabetes and its complications." (PMID 40642506, 2025). "On the other hand, Ism1 levels increased significantly in people with diabetes receiving metformin treatment at the end of 12 weeks (p = 0.028)." (PMID 40142334, 2025). "Ablation of ISM1 impaired both basal and insulin-stimulated glucose uptake by adipocytes, whereas, therapeutic administration of recombinant ISM1 improved diabetes in diet-induced obese mice." (PMID 39119006, 2024). "Although much exploration is still needed regarding ISM1 research, its roles in hematopoiesis, tumor immunity, diabetes, and nonalcoholic fatty liver disease have thus far been revealed, indicating the great therapeutic potential of ISM1." (PMID 36995541, 2023). "To ensure that this association was not a peculiarity of the L-NAME model, we checked the expression of ISM1 in four additional renal disease models: doxorubicin-induced nephropathy and diabetes, PAN, and LPS." (PMID 36769045, 2023). "The secreted protein isthmin-1 (Ism1) mitigates diabetes by increasing adipocyte and skeletal muscle glucose uptake by activating the PI3K-Akt pathway." (PMID 36169399, 2022). "As expected, many genes merely changed in the sDM group, such as SULF2, GFAP, ABCG1, GCK, ISM1, and CORIN, have been associated with diabetes." (PMID 34880765, 2021). "However, in both cases, Ism1 has been interpreted as an independent protective adipokine in diabetes due to its effects." (PMID 40142334, 2025). "In the literature, results have been found that Ism1 increases or decreases in diabetes." (PMID 40142334, 2025).
diabetes (continued). "Given that pre-diabetes is a critical stage where intervention can prevent the progression to T2D, Ism1 could potentially serve as a valuable biomarker for the early identification of individuals at risk." (PMID 39857685, 2025). "The increase of serum Ism1 was associated with a decreased risk of diabetes, and it did not reduce the risk of non-alcoholic fatty liver disease in diabetic patients." (PMID 35712241, 2022). "ISM1 may improve metabolic diseases by reducing oxidative stress and lipid peroxidation because oxidative stress and lipid peroxidation are closely related to diabetes, obesity, and MASLD." (PMID 39897276, 2025). "In addition, oxidative stress and lipid peroxidation are associated with obesity, diabetes, and NAFLD, and ISM1 may improve metabolic diseases by reducing oxidative stress and lipid peroxidation." (PMID 36995541, 2023). "Consistently, the prevalence of diabetes, PH and IPH were also found to be remarkably higher in men with the lowest tertile of ISM1 expression (P <0.05)." (PMID 39119006, 2024). "ISM1 expression was also explored in different rodent models of glomerulopathy: L-NAME, puromycin aminonucleoside (PAN), doxorubicin in rats and diabetes (ob/ob), and LPS in mice." (PMID 36769045, 2023). "Compared to people with no diabetes (reference group), a one-unit increase in Ism1 resulted in a 12% decrease in the pre-diabetes odds after adjusting for all other covariates included in the model." (PMID 39857685, 2025). "The proportion of low circulating Ism1 levels (<3.02 ng/ml) was higher in the diabetes group than the non-diabetic groups (P=0.015)." (PMID 35712241, 2022). "Our analysis implies that higher levels of Ism1 could potentially provide a protective effect against pre-diabetes or T2D compared to people without diabetes." (PMID 39857685, 2025). "Besides, it has also been reported that ISM-1 indirectly promotes pancreatic β cell dysfunction through NODAL (a member of the transforming growth factor superfamily), thereby accelerating the transition from pre-diabetes to type 2 diabetes." (PMID 40642506, 2025). "Additionally, compared to the reference group, people with no diabetes showed that a one-unit increase in Ism1 resulted in a 12.8% decrease in the odds of having T2D after adjusting for all other covariates included in the model." (PMID 39857685, 2025). "In a similar fashion, no obvious difference in ISM1 levels between females with different glycemic statuses or metabolic comorbidities was found (all P values >0.05), while significantly lower ISM1s were observed in males with diabetes, PH and IPH (P <0.05)." (PMID 39119006, 2024). "However, we found no apparent alterations in circulating Ism1 levels between diabetes and diabetes-associated NAFLD subjects, which did not support Ism1 as an independent risk factor for diabetes-associated NAFLD by logistic regression analysis." (PMID 35712241, 2022). "Additionally, the amount of ISM1 in the bloodstream has been found to be lower in obese individuals with T2DM than in obese individuals without T2DM; this supports the idea that high ISM1 levels may reduce the likelihood of developing diabetes." (PMID 39897276, 2025).
Obesity (9 papers, 2022 to 2025). Accumulation of substantial excess body fat. "Recent studies identify ISM1 as an adipokine that stimulates glucose uptake, inhibits lipid synthesis, stimulates protein synthesis, and is associated with obesity in adipocytes and female plasma." (PMID 39897276, 2025). "Our ROC results indicate that serum Ism1 levels possess significant diagnostic capability for identifying individuals with obesity." (PMID 39857685, 2025). "Considering the strong association between Ism1 and obesity, we evaluated the diagnostic potential of circulating Ism1 for obesity using ROC analysis." (PMID 39857685, 2025). "In the present work, we show higher serum levels of the novel insulin-like adipokine ISM1 in pubertal children with obesity, with an association with BMI Z-score and fat mass in boys." (PMID 36595188, 2023). "In conclusion, the circulating levels of the novel insulin-like adipokine ISM1 are significantly higher in pubertal children with obesity and are associated with BMI Z-score and fat mass in boys." (PMID 36595188, 2023). "Furthermore, our ROC results indicate that circulatory Ism1 levels possess significant diagnostic capability for identifying individuals with obesity-related metabolic imbalances with an area under the curve of 0.764 (95% CI = 0.718, 0.811)." (PMID 39857685, 2025). "Furthermore, we reveal two DNA methylations in two-enhancer-related CpG sites of the ISM1 region associated with serum levels of the protein in children with obesity." (PMID 36595188, 2023). "Furthermore, we identified DNA methylation in two-enhancer-related CpG sites of the ISM1 region (cg14269097 and cg14269097) associated with serum ISM1 levels in children with obesity." (PMID 36595188, 2023). "ISM1 is associated with obesity in boys at the pubertal stage, elucidating how this protein might be of special relevance as a new biomarker of obesity in children." (PMID 36595188, 2023). "This study aimed to estimate the correlation between Ism1 levels and several anthropometric and blood biomarkers in the Kuwait population and investigate its potential association with metabolic disease risk factors such as obesity, insulin resistance, MAFLD, and T2D." (PMID 39857685, 2025). "As a result, our logistic regression analysis suggests Ism1 as an independent protective factor to monitor obesity progression." (PMID 39857685, 2025). "Our analysis indicated that Ism1, SBP, TG, HDL cholesterol, HOMA-IR, and CAP scores are significantly and independently associated with obesity." (PMID 39857685, 2025). "Our findings further corroborate the protective role of Ism1 and highlight its potential utility as a biomarker for monitoring obesity-related metabolic diseases." (PMID 39857685, 2025). "Our data showed a significant reduction in Ism1 levels in people with obesity, in addition to increases in insulin resistance and MAFLD indicated by increased HOMA-IR and CAP scores, respectively." (PMID 39857685, 2025). "Logistic regression analysis further supported Ism1 as an independent significant protective factor against obesity-related metabolic dysfunction." (PMID 39857685, 2025). "To further explore the relationship between obesity and various variables including Ism1, we employed univariate analysis." (PMID 39857685, 2025). "Our finding of sexual dimorphism of ISM1 was further supported by a recent report that ISM1 was only significantly higher in pubertal boys with obesity." (PMID 39119006, 2024). "It proposes ISM1 as a novel non-invasive biomarker to predict abdominal fat partitioning and, consequently, to evaluate obesity-related health risks." (PMID 38066623, 2023). "In this series of 119 pubertal children, we show higher ISM1 levels in children with obesity compared to normal weight and overweight and a robust positive association between ISM1 serum levels and BMI Z-score in boys, indicating a putative sexual dimorphism." (PMID 36595188, 2023).
Obesity (continued). "Higher ISM1 serum levels were observed in boys with obesity when compared with normal weight (P = 0.004) and overweight (P = 0.007), un-adjusted." (PMID 36595188, 2023). "Lastly, we performed a correlation analysis among plasma ISM1 and other metabolic parameters to obtain some clues about the potential role of ISM1 in metabolic regulation in obesity." (PMID 38066623, 2023). "This population was intended as a discovery population to elucidate the relationship between obesity and ISM1 levels in children." (PMID 36595188, 2023). "Higher serum ISM1 levels were observed in boys with obesity than in normal weight (P = 0.004) and overweight (P = 0.007) boys." (PMID 36595188, 2023). "ISM1 positively correlates with obesity in human and mouse adipocytes, and in the plasma of females." (PMID 36995541, 2023). "Ism1 adipose expression and circulating levels are elevated in mice and humans with obesity, suggesting that the expression is under nutrient-sensing regulatory control." (PMID 36169399, 2022). "In this study, Ism1 levels may have been shaped by both obesity, gender and severe hormonal changes." (PMID 40142334, 2025). "On the other hand, the obesity of male adolescents may also have contributed to the increase in Ism1." (PMID 40142334, 2025). "Ism1 is a newly studied adipokine with potential roles in obesity and T2D, in particular." (PMID 39857685, 2025). "Collectively, our findings suggested a potential protective role for Ism1 against obesity and its complications, indicating it as a potential biomarker or diagnostic tool for early detection of metabolic diseases, warranting further investigation into its therapeutic potential." (PMID 39857685, 2025). "Insulin resistance was assessed using the homeostasis model assessment of insulin resistance (HOMA-IR), and fatty liver was evaluated using Fibroscan; Results: Our results showed a significant reduction in circulating Ism1 levels in individuals with obesity (p-value = 0.002)." (PMID 39857685, 2025). "Furthermore, the study population had blood whole-genome DNA methylation examined, allowing deepening into the obesity–ISM1 molecular relationship." (PMID 36595188, 2023). "We found a relationship between circulating ISM1 levels and obesity in pubertal children." (PMID 36595188, 2023). "Serum levels of the novel insulin-like adipokine ISM1 are indeed associated with obesity in boys at the pubertal stage but not in girls in a well-characterized population of Spanish children under a cross-sectional design." (PMID 36595188, 2023). "Nonetheless, the observed higher circulating ISM1 levels in pubertal children suggest that ISM1 resistance may be present, as administration of ISM1 into mice with established disease improves glucose and lipid dysfunction in diet-induced obesity." (PMID 36595188, 2023). "Both ISM1 and leptin seem to be expressed mainly by scWAT, increasing their levels in obesity." (PMID 38066623, 2023). "ISM1 could predict abdominal fat partitioning and be a potential biomarker for evaluating obesity-related health risks." (PMID 38066623, 2023). "In a high-fat diet-induced obesity and nonalcoholic fatty liver mouse model, injection of recombinant ISM1 can effectively reverse hepatic steatosis, which may provide a new direction for clinical treatment of metabolic diseases." (PMID 36995541, 2023). "Furthermore, we observed reduced levels of circulating Ism1 in people with obesity and MAFLD." (PMID 39857685, 2025). "Therefore, our research hypothesis was that epigenetic alterations in ISM1 could be relevant for understanding its role in obesity." (PMID 36595188, 2023). "Additionally, adjusted analysis demonstrated that increased Ism1 and HDL levels have a protective effect against obesity." (PMID 39857685, 2025). "In this study, we aimed to investigate the circulatory levels of Ism1 in individuals with obesity compared to non-obese individuals and evaluate their association with insulin resistance, MAFLD, and T2D." (PMID 39857685, 2025).
Obesity (continued). "This group of participants was presented with significantly reduced levels of circulating Ism1 (3.15 ng/mL) compared to those without obesity (5.17 ng/mL)." (PMID 39857685, 2025). "Non-invasive method of testing ISM1, MMP-8 and asprosin could be an effective reference tool for evaluating periodontitis in patients with obesity." (PMID 41063065, 2025). "In this study, we investigated the circulating Ism1 as a potential biomarker for conditions of metabolic diseases in a well-phenotyped population of individuals with obesity compared to those without obesity." (PMID 39857685, 2025). "All in all, ISM1, MMP-8 and asprosin might be potential biomarkers in periodontitis with obesity." (PMID 41063065, 2025). "The negative association between ISM1 and MPO suggests that the all-circulating levels of ISM1 in children with obesity might have a non-adipose cell origin." (PMID 36595188, 2023). "We found a correlation with obesity but not with HOMA-IR in children, which would point to the adipocyte-secreted protein ISM1 having a direct role in obesity but not in the metabolic status derived from IR." (PMID 36595188, 2023). "Additionally, participants with obesity presented significantly increased insulin resistance reflected by a higher HOMA-IR median and a significant increase in the median of CAP scores, while showing significantly lower Ism1 median levels compared to the non-obese group." (PMID 39857685, 2025).